DAAM2 (dishevelled associated activator of morphogenesis 2)
Description:
Key regulator of the Wnt signaling pathway, which is required for various processes during development, such as dorsal patterning, determination of left/right symmetry or myelination in the central nervous system. Acts downstream of Wnt ligands and upstream of beta-catenin (CTNNB1). Required for canonical Wnt signaling pathway during patterning in the dorsal spinal cord by promoting the aggregation of Disheveled (Dvl) complexes, thereby clustering and formation of Wnt receptor signalosomes and potentiating Wnt activity. During dorsal patterning of the spinal cord, inhibits oligodendrocytes differentiation via interaction with PIP5K1A. Also regulates non-canonical Wnt signaling pathway. Acts downstream of PITX2 in the developing gut and is required for left/right asymmetry within dorsal mesentery: affects mesenchymal condensation by lengthening cadherin-based junctions through WNT5A and non-canonical Wnt signaling, inducing polarized condensation in the left dorsal mesentery necessary to initiate gut rotation. Together with DAAM1, required for myocardial maturation and sarcomere assembly. Is a regulator of actin nucleation and elongation, filopodia formation and podocyte migration.
Synonyms: KIAA0381; NPHS24; dJ90A20A.1
Tractability: No criterion of Open Targets' tractability assessment is met for any kind of drug.
Gene: Protein-coding gene on chromosome 6 (39,792,298 to 39,904,877, forward strand). Ensembl gene ENSG00000146122.
Subcellular location (Human Protein Atlas): Nucleoplasm; Cytosol; Vesicles
Gene Ontology:
Molecular function: protein binding; actin binding; small GTPase binding
Biological process: podocyte cell migration; positive regulation of cell migration; regulation of actin cytoskeleton organization; regulation of actin filament polymerization; regulation of filopodium assembly; dorsal spinal cord development; negative regulation of oligodendrocyte differentiation; positive regulation of canonical Wnt signaling pathway; regulation of canonical Wnt signaling pathway; regulation of non-canonical Wnt signaling pathway; actin cytoskeleton organization
Cellular component: extracellular exosome; nucleoplasm
Genetic constraint (gnomAD): Loss-of-function variants: 36 observed, 97.42 expected, observed/expected ratio (o/e) 0.37, 90% interval 0.28 to 0.49. The upper end of that interval is the gene's LOEUF score, 0.49, which puts it in group 2 of 6, group 1 being the genes least tolerant of losing a copy. Missense variants: 1,179 observed, 1,264.1 expected, observed/expected ratio (o/e) 0.93, 90% interval 0.89 to 0.98. Synonymous variants: 454 observed, 473.02 expected, observed/expected ratio (o/e) 0.96, 90% interval 0.89 to 1.04.
Gene-disease validity (ClinGen):
ClinGen rates the evidence that DAAM2 causes each of these diseases.
idiopathic multidrug-resistant nephrotic syndrome (autosomal recessive): Limited.
Homologues: Orthologues: chimpanzee DAAM2 (99% identical), macaque DAAM2 (99% identical), dog DAAM2 (97% identical), pig DAAM2 (97% identical), rabbit DAAM2 (96% identical), guinea pig DAAM2 (94% identical), mouse Daam2 (92% identical), rat Daam2 (92% identical), tropical clawed frog daam2 (79% identical), zebrafish daam2 (72% identical), Caenorhabditis elegans daam-1 (24% identical). Paralogues in human: DAAM1 (69% identical), FMNL2 (24% identical), FMNL1 (24% identical), FMNL3 (24% identical), DIAPH1 (23% identical), DIAPH2 (22% identical), DIAPH3 (21% identical), INF2 (21% identical), FHOD3 (18% identical), FMN2 (17% identical), GRID2IP (17% identical), FHOD1 (16% identical), and 6 more.
Diseases named in the same sentence as DAAM2 in open-access papers:
DAAM2 is named in the same sentence as 39 diseases in open-access papers, as found by Europe PMC text mining. Sharing a sentence is not in itself a finding about the gene and the disease. The quoted sentences say what the papers report.
osteoporosis (6 papers, 2019 to 2025). A condition of reduced bone mass, with decreased cortical thickness and a decrease in the number and size of the trabeculae of cancellous bone (but normal chemical composition), resulting in increased fracture incidence. "Numerous osteoporosis susceptibility loci, including ESR1, LRP4, DAAM2, WNT 16, and SOX 6, have been found and investigated using multiomics techniques based on systems genetics and genomics." (PMID 35496311, 2022). "DAAM2 also may be a potential drug target for osteoporosis as it shows effects on bone strength, porosity, and quality in murine models by indirect regulation of the canonical Wnt signaling." (PMID 30820831, 2019). "DAAM2 serves as a pivotal downstream effector for SIRT1 to exert immune-regulatory effects in the bone microenvironment; thus, targeting DAAM2 can treat osteoporosis by increasing CD4+ CTL responses." (PMID 40714829, 2025).
COVID-19 (3 papers, 2022 to 2025). A disease caused by infection with severe acute respiratory syndrome coronavirus 2. "In a large, prospective, multicenter cohort, we find that either a single gene, OLAH, or a combination of 3 genes, CD83, ATP1B2, and DAAM2, accurately predicted 28-day mortality in hospitalized patients with COVID-19, including those who have been vaccinated." (PMID 41212055, 2025). "It is not inconceivable that, subsequent to SARS-CoV-2 infection, autoantibodies against the DAAM2 or CHL1 proteins can be produced that may contribute to the neurological manifestations of COVID-19." (PMID 41009363, 2025).
breast carcinoma (2 papers, 2019 to 2023). "Consistent with the notion that DAAM1 inhibits and DAAM2 promotes ACM-induced BCC migration, decreased expression of DAAM1 in breast cancer patients resulted in a significant reduction in survival." (PMID 31142743, 2019).
cervical cancer (2 papers, 2022). A primary or metastatic malignant neoplasm involving the cervix. "In addition, in an immune-related classification strategy for cervical cancer, DAAM2 was used as one of the critical genes for risk demarcation." (PMID 35281277, 2022). "A bioinformatic study revealed that a signature comprising four genes (RIPOR2, DAAM2, SORBS1, CXCL8) was found to be associated with survival in cervical cancer patients." (PMID 36497200, 2022).
focal glomerulosclerosis (2 papers, 2022 to 2024). "Interestingly, Daam2 and Cd151 have recently been reported to be upregulated in a dataset of human focal glomerulosclerosis." (PMID 39278930, 2024).
glioma (2 papers, 2017 to 2022). A benign or malignant brain and spinal cord tumor that arises from glial cells (astrocytes, oligodendrocytes, ependymal cells). "To identify changes in protein expression associated with Daam2-mediated tumorigenesis we performed reverse phase protein lysate microarray (RPPA) on FACS-isolated mouse glioma samples that overexpress Daam2." (PMID 29053101, 2017). "To further delineate the role of Daam2 in glioma, we next performed a series of complementary loss-of-function (LOF) studies in human and mouse glioma models." (PMID 29053101, 2017). "(G–J) Representative immunohistochemical analysis of Akt pS473 expression in CRISPR-IUE glioma tumors derived from Daam2-overexpression (H) or knockout of Daam2 (J) and associated controls." (PMID 29053101, 2017). "(C–F) Representative immunohistochemical analysis of VHL expression in CRISPR-IUE glioma tumors derived from Daam2-overexpression (D) or knockout of Daam2 (F) and associated controls." (PMID 29053101, 2017). "The expression analysis in human glioma and associated mouse models led us to examine whether Daam2 contributes to glioma tumorigenesis." (PMID 29053101, 2017). "The oncogenic role of DAAM2 has been confirmed in glioma and hepatocellular carcinoma, but the biological function of DAAM2 in PAAD needs to be further explored." (PMID 35281277, 2022). "Having established that Daam2 functions to promote glioma tumorigenesis, we next sought to uncover the mechanism by which it operates." (PMID 29053101, 2017). "Our mechanistic studies revealed that Daam2 promotes glioma tumorigenesis via suppression of VHL, a classic tumor suppressor that promotes HIF1α degradation and inhibits Akt activity." (PMID 29053101, 2017). "(A) Heatmap analysis of RPPA data showing the core cohort of proteins downregulated by overexpression of Daam2 in the PB-Ras mouse glioma model." (PMID 29053101, 2017). "Using protein lysates extracted from our PB-Ras model of glioma, we found that Daam2 co-immunoprecipitates with VHL (and vice versa), suggesting that these proteins associate." (PMID 29053101, 2017). "Another possibility to consider is that Daam2 dysregulation is a passive by-product of its expression in a cell lineage that is over-represented in glioma." (PMID 29053101, 2017). "Towards this we took advantage of the TCGA pan-cancer expression data set and evaluated Daam2 expression across a spectrum of 34 malignancies, finding that it’s most highly expressed in low-grade glioma (LGG) and glioblastoma multiforme (GBM)." (PMID 29053101, 2017). "(D) Immunohistochemistry analysis of Daam2-LacZ expression in mouse glioma generated in Daam2LacZ/+ mice." (PMID 29053101, 2017). "Leveraging existing TCGA expression data across a broad spectrum of malignancies, we found that Daam2 is most highly expressed in glioma and melanoma." (PMID 29053101, 2017). "Analysis revealed a cohort of proteins that are strongly downregulated in glioma samples that overexpress Daam2." (PMID 29053101, 2017). "Using developmental processes to uncover new pathways contributing to tumorigenesis, we found that Daam2 promotes glioma formation." (PMID 29053101, 2017). "(F–H) Representative bioluminescence imaging of mice bearing CRISPR-IUE glioma generated in Daam2 ± or Daam2-/- mice, imaged at 8 weeks of age." (PMID 29053101, 2017). "Together, these studies represent the initial characterization of Daam2 function in glioma and define, for the first time, an upstream regulatory mechanism that controls VHL protein expression in cancer." (PMID 29053101, 2017). "Together, our LOF, and complementing GOF studies in human and mouse models of glioma indicate that Daam2 promotes cell proliferation and tumorigenesis." (PMID 29053101, 2017). "(G–I) Representative bioluminescence imaging of mice bearing CRISPR-IUE glioma with Daam2 overexpression or control, imaged at 7 weeks of age." (PMID 29053101, 2017).
glioma (continued). "Deciphering which scenario (passive or active) is responsible for Daam2 dysregulation in glioma is an important area of future investigation." (PMID 29053101, 2017). "Put together, these data indicate that Daam2 promotes tumorigenesis by suppressing VHL expression in glioma." (PMID 29053101, 2017). "To further evaluate the necessity for Daam2 in glioma tumorigenesis, we used CRISPR/IUE model to generate malignant glioma in Daam2+/- and Daam2−/− mice." (PMID 29053101, 2017). "These knockdown studies across both in vitro and in vivo systems, complement the overexpression studies, and further substantiate the role of Daam2 in glioma cell proliferation and tumorigenesis." (PMID 29053101, 2017). "These expression characteristics in glioma were confirmed using tissue arrays and functional studies revealed that Daam2 promotes cell proliferation and tumorigenesis in human and mouse glioma models." (PMID 29053101, 2017). "(B) Examples of pathological grading of in situ hybridization analysis of Daam2 expression in human glioma tissue microarrays." (PMID 29053101, 2017). "Finally, our observations that Daam2 expression is increased in a majority of glioma tumors raises the question how it becomes dysregulated." (PMID 29053101, 2017). "Using factors critical for central nervous system (CNS) development as an entry point to identify new mechanisms that contribute to tumorigenesis, we found that the glial development factor, Daam2 promotes glioma tumorigenesis across human glioma cell lines and multiple mouse models of glioma." (PMID 29053101, 2017). "The RPPA data suggests that Daam2 modulates expression of VHL in glioma." (PMID 29053101, 2017). "Notably, the majority of tumors exhibited staining intensity scores that exceeded normal brain samples, indicating that Daam2 expression is elevated within glioma tumors." (PMID 29053101, 2017). "Moreover, the RPPA data analysis identified a larger cohort of proteins that were downregulated in the presence of Daam2 in our mouse model of glioma." (PMID 29053101, 2017). "Previously, we found that Daam2 functions as a positive regulator of Wnt-signaling in the developing CNS, suggesting that it may also function in this manner in glioma." (PMID 29053101, 2017). "This, coupled with the fact that Daam2 acts upon existing Wnt receptor complexes, may explain why we did not witness any overt changes in Wnt activity when we manipulated Daam2 expression in our glioma models." (PMID 29053101, 2017). "Thus, future studies may also be geared towards delineating the links between Daam2 and these other downregulated candidates (i.e. Claudin-7 and Syk, etc.)in the context of glioma and glial development." (PMID 29053101, 2017). "To assess its role in glioma, we performed overexpression, gain-of-function (GOF) studies in human GBM cell lines, finding that Daam2 accelerates the rate of cell growth in vitro." (PMID 29053101, 2017). "Next, we extended these studies to our mouse models of glioma, finding that combined overexpression of VHL with Daam2 similarly suppressed the accelerated rate of tumorigenesis and proliferation mediated by Daam2-alone." (PMID 29053101, 2017). "Protein expression screening identified an inverse correlation between Daam2 and VHL expression across a host of cancers, including glioma." (PMID 29053101, 2017). "To evaluate Wnt-activity we used an established Wnt-reporter (TOP-FLASH) and found that modulation of Daam2 expression has a modest effect on Wnt activity in glioma cell lines and did not impact Wnt activity in our mouse model of glioma." (PMID 29053101, 2017). "To validate DAAM2 expression in human LGG and GBM, we used in situ hybridization (ISH) across a cohort of 35 LGG and 40 GBM primary human samples, finding that DAAM2 demonstrates heterogeneous expression within each glioma sub-type." (PMID 29053101, 2017).
glioma (continued). "That Wnt-activity is not affected by changes in Daam2 expression raises the question of how Daam2 promotes glioma tumorigenesis." (PMID 29053101, 2017). "Nevertheless, we cannot formally rule out a possible role for Daam2 in canonical or non-canonical Wnt signaling in glioma or in other malignancies driven by Wnt dysregulation." (PMID 29053101, 2017). "In addition, we assessed DAAM2 expression via qRT-PCR in primary human glioma samples and non-tumor white matter, and consistent with the tissue microarray data, we found that Daam2 expression is elevated in a majority of these primary samples." (PMID 29053101, 2017).
nephrotic syndrome (2 papers, 2024). A collection of symptoms that include severe edema, proteinuria, and hypoalbuminemia; it is indicative of renal dysfunction. "Notably, the most down-regulated transcript, dishevelled-associated activator of morphogenesis 2 (DAAM2), has variants linked to the development of nephrotic syndrome, in which the renal microvasculature is disrupted." (PMID 38978787, 2024).
neuroblastoma (2 papers, 2013 to 2017). Neuroblastoma (NB) is the most common solid, extracranial childhood tumor. "Recent studies have implicated Daam1, Daam2 and other formin-family genes in the migration of breast and neuroblastoma cell lines, respectively, suggesting that the Daam-family proteins may also contribute to invasion and metastasis in other malignancies." (PMID 29053101, 2017).
androgen insensitivity syndrome (1 paper, 2024). Androgen insensitivity syndrome (AIS) is a disorder of sex development (DSD) characterized by the presence of female external genitalia, ambiguous genitalia or variable defects in virilization in a 46,XY individual with absent or partial responsiveness to age-appropriate levels of androgens. "In vitro studies of genital skin-derived fibroblasts (GSFs) from patients with androgen insensitivity syndrome (AIS) type II and DAAM2 variants showed reduced dihydrotestosterone (DHT)-induced AR activity compared to WT GSFs." (PMID 39337600, 2024).
bladder cancer (1 paper, 2019). "Furthermore, reduced expression of DAAM1 and elevated expression of DAAM2 were associated with high-grade bladder cancer." (PMID 31142743, 2019).
fetal growth restriction (1 paper, 2021). A fetus that does not grow beyond the 10th percentile of conventionally accepted weight for gestational age. "Thus, circulating DAAM2 mRNA expression demonstrated potential to highlight pregnancies at serious risk of preterm fetal growth restriction and may be useful in a multi-marker test." (PMID 33692394, 2021). "In this study, we aimed to assess whether DAAM2 was expressed in the human placenta and whether gene expression or protein production was altered by gestation, or placental dysfunction associated with preterm fetal growth restriction." (PMID 33692394, 2021). "Previously, we identified increased maternal circulating DAAM2 mRNA in pregnancies complicated by preterm fetal growth restriction (FGR)." (PMID 33692394, 2021). "In this paper, we identified that circulating DAAM2 mRNA has potential to detect fetal growth restriction (FGR), is expressed in the human placenta throughout gestation and is dysregulated with hypoxia and in disease settings." (PMID 33692394, 2021). "It is important to note that in the placental samples available to examine DAAM2 mRNA expression, there was a significant difference in gestational age between our controls and fetal growth restriction-complicated pregnancies." (PMID 33692394, 2021). "We log-transformed circulating DAAM2 mRNA expression, demonstrating a highly significant increase (p < 0.0001) in circulating DAAM2 mRNA in pregnancies complicated by preterm fetal growth restriction compared to gestation-matched controls." (PMID 33692394, 2021). "Consistent with our discovery in the maternal circulation, we identified an increase in DAAM2 protein in human placental tissue from pregnancies complicated by early onset fetal growth restriction." (PMID 33692394, 2021). "In this report, we demonstrated increases in DAAM2 expression in placentas complicated by early onset fetal growth restriction and hypoxia, indicating a potential role in the dysfunctional placenta." (PMID 33692394, 2021). "However, placental DAAM2 protein was significantly increased in pregnancies complicated by preterm fetal growth restriction, compared to gestation-matched control placentas (p = 0.049)." (PMID 33692394, 2021). "DAAM2 mRNA was elevated in the circulation of women with preterm fetal growth restriction." (PMID 33692394, 2021). "Importantly, in these placental studies we assessed DAAM2 protein and mRNA expression in samples where corticosteroids were given in both the controls and pregnancies complicated by fetal growth restriction." (PMID 33692394, 2021).
Guillain-Barre syndrome (1 paper, 2020). A spectrum of rare post-infectious neuropathies that usually occur in otherwise healthy patients. "Another study demonstrated a correlation between decreased DAAM2 expression and improvements in remyelination in Guillain- Barre syndrome, suggesting that IFNγ may activate specific pathways redirecting the process." (PMID 32511247, 2020).
hypospadias (1 paper, 2020). Hypospadias is the displacement of the urethral meatus on the ventrum of the penis. "We identified methylation at cg15242360 as associated with hypospadias severity, which is located in the DAAM2 region." (PMID 32728162, 2020).